ZNF831 (zinc finger protein 831)
Synonyms: C20orf174; dJ492J12.1
Tractability: Small molecule: a structure with a bound ligand is known. PROTAC: ubiquitination databases record sites on it.
Gene: Protein-coding gene on chromosome 20 (59,123,381 to 59,259,113, forward strand). Ensembl gene ENSG00000124203.
Gene Ontology:
Molecular function: protein binding
Genetic constraint (gnomAD): Loss-of-function variants: 59 observed, 89.21 expected, observed/expected ratio (o/e) 0.66, 90% interval 0.54 to 0.82. The upper end of that interval is the gene's LOEUF score, 0.82, which puts it in group 3 of 6, group 1 being the genes least tolerant of losing a copy. Missense variants: 2,205 observed, 2,137.2 expected, observed/expected ratio (o/e) 1.03, 90% interval 1 to 1.07. Synonymous variants: 961 observed, 914.43 expected, observed/expected ratio (o/e) 1.05, 90% interval 1 to 1.11.
Homologues: Orthologues: chimpanzee ZNF831 (99% identical), macaque ZNF831 (91% identical), dog ZNF831 (62% identical), pig ZNF831 (60% identical), rabbit ZNF831 (60% identical), guinea pig ZNF831 (58% identical), mouse Zfp831 (56% identical), rat Zfp831 (55% identical), tropical clawed frog znf831 (25% identical), zebrafish znf831 (16% identical). Paralogues in human: HIVEP1 (20% identical), HIVEP2 (17% identical), HIVEP3 (17% identical), RREB1 (10% identical), SALL3 (8% identical), SALL1 (7% identical), SALL4 (6% identical), SALL2 (6% identical), ZNF536 (6% identical), BCL11B (5% identical), BCL11A (5% identical), ZNF516 (5% identical), and 2 more.
Diseases named in the same sentence as ZNF831 in open-access papers:
ZNF831 is named in the same sentence as 19 diseases in open-access papers, as found by Europe PMC text mining. Sharing a sentence is not in itself a finding about the gene and the disease. The quoted sentences say what the papers report.
preeclampsia (4 papers, 2020 to 2026). Preeclampsia is a hypertensive disorder of pregnancy that is characterized by new-onset hypertension with proteinuria presenting after 20 weeks of gestation, and depending on mild or severe forms may initially present with severe headache, visual disturbances, and hyperreflexia. "TGIF1 and its targets, including ADAM12, WNT3A, and ZNF831, are associated with preeclampsia and pregnancy loss." (PMID 42103736, 2026). "To better understand the contribution of molecular polygenic risk factors to the development of preeclampsia, we studied the relationship between rs259983 of the ZNF831 gene and this pathology in pregnant women with GDM." (PMID 39456889, 2024). "Before studying the potential relation between rs259983 of the ZNF831 gene and preeclampsia, we calculated the frequency of genotypes and allele occurrences." (PMID 39456889, 2024). "In genome-wide association meta-analysis of European and Central Asian mothers, we identify sequence variants that associate with preeclampsia in the maternal genome at ZNF831/20q13 and FTO/16q12." (PMID 33239696, 2020). "The ZNF831 variants rs259983 and rs6015450, identified through the preeclampsia meta-analysis and thorough testing of BP variants, respectively, are in strong LD (r2 = 0.74 in European data)." (PMID 33239696, 2020). "We obtained similar results by examining the relationship between rs259983 of the ZNF831 gene and preeclampsia, excluding obese women and CHTN from the analysis." (PMID 39456889, 2024). "An association was found between carriers of the AC and CC genotypes rs259983 of the ZNF831 gene and superimposed preeclampsia." (PMID 39456889, 2024). "The allele C of the rs259983 polymorphism of the ZNF831 gene increases the risk of developing SIPE, which in turn increases the risk of developing preeclampsia by 1.7 times." (PMID 39456889, 2024). "The novelty of the research is also significant as we provide the first case-control study that estimates the relationship between rs259983 of the ZNF831 gene, preeclampsia, and SIPE in pregnant women with GDM." (PMID 39456889, 2024). "We thus conclude that in addition to the variants near ZNF831 and FTO that exhibited genome-wide significance, BP variants at FGF5, SH3B2, and MECOM also associate with preeclampsia." (PMID 33239696, 2020). "We found that the four preeclampsia associated variants at MECOM, FGF5, ZNF831, and SH2B3 are among the variants with the highest effect on all three BP traits, particularly on diastolic BP." (PMID 33239696, 2020). "As a result of our study, no connection with rs259983 of the ZNF831 gene was identified among women without risk factors for preeclampsia (obesity and CHTN)." (PMID 39456889, 2024). "Therefore, our goal was to examine the relationship between rs259983 of the ZNF831 gene and preeclampsia in pregnant women with GDM." (PMID 39456889, 2024). "The potential connection between rs259983 of the ZNF831 and preeclampsia was then examined." (PMID 39456889, 2024). "We suggested that superimposed preeclampsia may be more strongly related to rs259983 of the ZNF831 gene." (PMID 39456889, 2024). "A previous GWAS found a relationship between rs259983 of the ZNF831 gene and HDP, such as for chronic hypertension (CHTN) and preeclampsia (PE)." (PMID 39456889, 2024).
breast carcinoma (2 papers, 2022 to 2024). "Study has revealed that ZNF831 knockdown enhances proliferation of breast cancer cells, suggesting that ZNF831 mutations may contribute to cancer progression." (PMID 38970307, 2024).
gestational diabetes (2 papers, 2024 to 2025). Carbohydrate intolerance first diagnosed during pregnancy. "We conducted the case-control study to determine the association between rs259983 of the ZNF831 gene and HDP in women with Gestational Diabetes Mellitus (GDM)." (PMID 39456889, 2024). "The aim of this study was to investigate the relationship between rs259983 of the zinc finger protein 831 (ZNF831) gene and anemia in pregnant women with gestational diabetes mellitus (GDM)." (PMID 40475810, 2025).
Hypertension (2 papers, 2024). The presence of chronic increased pressure in the systemic arterial system. "According to UKBiobank TOPMed-imputed PheWeb, the rs259983 gene ZNF831 is associated with the following traits: hypertension complicating pregnancy, childbirth and the puerperium, and essential hypertension and hypertension." (PMID 39456889, 2024). "GWAS variant rs16982520, located within ZNF831, is associated with hypertension, systolic blood pressure and mean arterial pressure and interacts directly with EDN3 and four direct interactors of the putative regulatory region (GNAS, RP4-614C15." (PMID 38885195, 2024). "According to UKBiobank TOPMed-imputed PheWeb, the rs259983 gene ZNF831 is involved with the following traits: hypertension complicating pregnancy, childbirth and the puerperium, essential hypertension and hypertension, and calcium channel blocker use measurement and systolic blood pressure." (PMID 39456889, 2024).
triple-negative breast carcinoma (2 papers, 2021 to 2022). An invasive breast carcinoma which is negative for expression of estrogen receptor (ER), progesterone receptor (PR), and human epidermal growth factor receptor 2 (HER2). "ZNF831 is a transcription factor gene and was also significantly correlated with immune cell infiltration in triple negative breast cancer." (PMID 34733790, 2021).
anemia (1 paper, 2025). A reduction in the number of red blood cells, the amount of hemoglobin, and/or the volume of packed red blood cells. "The results of our study indicate that carriers of the C allele in the rs259983 homozygous state of the ZNF831 gene are at a higher risk of developing anemia." (PMID 40475810, 2025). "Carriers of the C allele in the homozygous state rs259983 of the ZNF831 are at greater risk of developing anemia." (PMID 40475810, 2025). "To better understand the contribution of molecular genetic risk factors to the development of anemia, we studied the relationship between rs259983 of the ZNF831 gene and this pathology in pregnant women with GDM." (PMID 40475810, 2025). "Carriers of the C allele in the rs259983 homozygous state of the ZNF831 gene are at greater risk of developing anemia." (PMID 40475810, 2025). "Our study found an association between rs259983 of the ZNF831 gene and the risk of anemia." (PMID 40475810, 2025). "As a result, an association was found between rs259983 of the ZNF831 gene and the risk of anemia." (PMID 40475810, 2025). "The study of ZNF831’s ability to bind metal ions, including zinc, may be related to anemia, since metal-binding proteins play a key role in the homeostasis of metals, such as iron and zinc, which are essential for hematopoiesis." (PMID 40475810, 2025). "According to in silico analysis, the ZNF831 protein is able to bind iron (FE, 0.69) and other ions, which may play an essential role in anemia pathogenesis." (PMID 40475810, 2025). "There is no scientific data on the association of rs259983 and other ZNF831 gene polymorphisms with anemia." (PMID 40475810, 2025). "Impaired function of ZNF831 can affect the metabolism of iron, a key component of hemoglobin, or zinc-dependent cell division and differentiation processes, which can ultimately contribute to the development of anemia." (PMID 40475810, 2025).
B-cell lymphoma (1 paper, 2025). "FOXP1 has previously been linked to B-cell lymphoma while ZNF831 is overall poorly studied." (PMID 39878215, 2025).
melanoma (1 paper, 2021). A malignant, usually aggressive tumor composed of atypical, neoplastic melanocytes. "ZNF831 may regulate tumor immune infiltration in melanoma and plays an important role in infiltration and immune escape from melanoma." (PMID 34616613, 2021). "Our results indicate that miR-3662 may repress melanoma cell proliferation, migration and invasion by down-regulating PKIA and ZNF831." (PMID 34616613, 2021).
tumor (6 papers, 2017 to 2025). "In summary, we found two potential tumor antigens, ZNF831 and SYNE1, and identified four immune subtypes of HCC with distinct molecular features." (PMID 40948427, 2025). "Two potential tumor antigens, ZNF831 and SYNE1, showed significant superior prognostic effects and positive correlations with antigen presenting cells, which provided promising candidates for the development of tumor antigen‐based mRNA vaccine." (PMID 40948427, 2025). "The most downregulated genes contained known tumor suppressors (ZNF831, AKNA, NR4A1, ARHGAP9, ZBTB16) and regulators of immune response (NLRC5, WDFY4, RASGRP2, IKZF1)." (PMID 39794830, 2025). "In the HPA database, protein expressions of the seven genes (ADAMTS8, CCR2, CYSLTR2, FAM129C, FCER1A, GAPT, PKHD1L1, and ZNF831) were markedly low in tumor tissues with less intense antibody staining and fewer stained cells in LUAD." (PMID 36033829, 2022). "Furthermore, two tumor antigens, ZNF831 and SYNE1, had positive correlations with antigen presenting cells." (PMID 40948427, 2025). "All these results implied that ZNF831 and SYNE1 may be promising candidates for tumor antigen based cancer vaccine development in HCC." (PMID 40948427, 2025). "We stratified basal tumours in Take and No Take groups and noted that the expression of ZNF831, IKZF3 and SP140 was lower in the Take compared with the No Take group (p < 0.05)." (PMID 28588211, 2017).
cancer (5 papers, 2018 to 2025). A tumor composed of atypical neoplastic, often pleomorphic cells that invade other tissues. "Third, the two identified tumor antigen genes, ZNF831 and SYNE1, which have the potential to aid the development of cancer vaccines, should be viewed as hypothesis generating rather than conclusions, because the causal effects of the correlations cannot be determined in the current study." (PMID 40948427, 2025).
ZNF831 also shares sentences with these, for which no sentence is quoted: Obesity (3 papers); depression (1); diabetes (1); essential hypertension (1); lung adenocarcinoma (1); metastatic melanoma (1); rheumatoid arthritis (1); schizophrenia (1); tendinitis (1).